AXL (AXL receptor tyrosine kinase)
Diseases named in the same sentence as AXL in open-access papers (continued):
Sharing a sentence is not in itself a finding about the gene and the disease.
cancer (continued). "In addition, AXL can activate other downstream signaling pathways, such as PI3K/AKT and MAPK/ERK, which are involved in cancer cell growth and survival." (PMID 37760491, 2023). "For instance, high AXL expression has been found in NSCLC patients with low response to EGFR tyrosine kinase inhibitor (TKI), as well as in erlotinib or osimertinib resistant cancer cell lines." (PMID 37328828, 2023). "In a comparison to AXL with an established role in enhancing resistance to ICB, CYTH4, DENND1C, AOAH, EPSTI1, and TBC1D10C display a stronger correlation with immune checkpoints in human cancers." (PMID 36588164, 2023). "Our study reveals the intricate interplay between AXL, MIG6 and EGFR signaling in cancer." (PMID 37834326, 2023). "Additionally, AXL suppression in xenograft-bearing mice decreases the endothelial cell marker CD31 in tumors and reduces cancer cell-triggered angiogenesis." (PMID 37265798, 2023). "Consistent with previous reports suggesting a crucial role of AXL in cancer cell migration, invasion, and metastasis, our results showed that GALNT2‐mediated invasion was significantly reversed by inhibiting AXL expression with pharmacologic or genetic approach." (PMID 36409270, 2023). "Notably, this coexpression pattern between AXL and MIG6 was confirmed in cancer cell lines and NSCLC patients, suggesting potential collaboration in regulating EGFR signaling." (PMID 37834326, 2023). "One of the mechanisms for AXL to help DTCs survival is proposed that AXL could bind to the ligand GAS6, while the activation of the GAS6/AXL axis can promote the dormancy of cancer cells." (PMID 37638338, 2023). "Moreover, hMENA/hMENAΔv6 isoforms were also shown to regulate AXL levels in cancer cells, whereas their silencing inhibited GAS6-induced AXL expression and AKT phosphorylation." (PMID 36422541, 2022). "Rather than functioning as a driver to initiate cancer transformation, AXL predominantly provides survival, metastatic signals and causes chemo-resistance." (PMID 35414783, 2022). "The studies indicated that targeting MET, AXL, and VEGFR2 may enhance the efficacy of immune checkpoint inhibitor for cancer patients, which can be explored in further study." (PMID 36341335, 2022). "It is thus plausible that rapid uptake of AXL and its subsequent recycling and delivery to nascent focal adhesions might play an important role during GAS6–AXL-induced cancer-cell migration and invasion." (PMID 35622156, 2022). "GAS6 expression in CAFs maintains the protumoral GAS6/AXL paracrine axis and has been described as serving a vital role in the EMT, drug resistance, and metastasis of multiple types of cancer." (PMID 36422541, 2022). "Therefore, it is expected that CT053PTSA will have exhibit performance in cancer patients with MET, AXL, VEGFR-2 and FLT3 overexpression." (PMID 36341335, 2022). "Further analysis of TAM-stimulated primary cancer cell clusters compared to naïve cell clusters revealed that c-Myc, PLAU, PLAUR, and AXL were significantly upregulated, while the downregulated epithelial marker (EPCAM) was observed in the disseminated cell clusters." (PMID 35680853, 2022). "Unlike in cancer cells, the downstream effectors of AXL signaling leading to cytokine secretion in immune cells have been well characterized." (PMID 35158733, 2022). "Additionally, a recent study revealed the role of CDRs in cancer cell invasion by their induction in LN229 cells and disassembly of focal adhesions after receptor tyrosine kinase AXL stimulation by GAS6 ligand." (PMID 35799301, 2022). "For example, AXL can activate several generic downstream effectors from such RTKs as MAPK, PI3K/AKT and JAK/STAT to promote actin reorganization, migration and survival of cancer cells." (PMID 35158733, 2022). "AXL is frequently overexpressed in cancer, which can increase the invasiveness and motility of the normally non-invasive MCF-7 cell line." (PMID 36186479, 2022).
cancer (continued). "Next, we expanded our analysis to a second cancer type, SKCM, and examined whether BayesPrism would recover expression differences characteristic of the AXL and MITF malignant cell states." (PMID 35469013, 2022). "In cancer cells, chemotherapy induces EMT and AXL is also upregulated in this context." (PMID 35158733, 2022). "In the syngeneic KPL model, AXL inhibitor acts primarily on DCs, rather than on carcinoma cells or macrophages, promoting DC-mediated type I interferon secretion, infiltration of the TCF1+PD-1+CD8 cells, and response to anti-PD-1." (PMID 35572601, 2022). "While AXL and MER have been thoroughly investigated, the role of TYRO3 in cancer development remains unknown." (PMID 34721022, 2021). "Likewise, LINC00346 functions as a sponge for miR-34a and promotes cancer cell proliferation, invasion, and metastasis in gastric cancer by protecting NOTCH1, AXL, and CD44 from miR-34a-mediated degradation." (PMID 33763422, 2021). "The AXL RTK has been connected to EMT, invasion, and metastasis in several cancers." (PMID 33921066, 2021). "In effect, several targeted therapies are selective and nonselective for AXL, which are in preclinical and clinical development in multiple cancer types." (PMID 34778071, 2021). "Despite the multifunctional roles of AXL in cancer initiation and progression and in regulating antitumor immune responses, the signaling network driven by AXL has not been fully characterized." (PMID 34439388, 2021). "If AXL kinase plays an important role in DT cell survival in ALK-rearranged cancer, the dual inhibition of ALK and AXL by gilteritinib might delay the emergence of additional acquired resistance and represent an important clinical option." (PMID 33627640, 2021). "Interestingly, the number of co-occurring genes regulating the EMT and cancer stem cell (CSC) programs correspond to the type of AXL alterations (i.e., high in AXL amplification, low in AXL deletion) at the copy number level." (PMID 33850249, 2021). "Lastly, we define two candidate genes potentially regulated by pBRD4 in JQ1 resistant LAC, AXL and SPOCK1, which cancers may become dependent on after adaptation to BETi treatment, offering additional avenues for therapeutic intervention." (PMID 33712563, 2021). "AXL/ALK/FLT3 inhibitors (e.g., gilteritinib) have shown promise as anti-cancer agents." (PMID 33917370, 2021). "Increasing studies have demonstrated the vital roles of TAM receptor-ligand complex in inflammation, immunity, and cancer, with the roles of TAM receptor AXL in PTC being proved by several independent research teams." (PMID 34414029, 2021). "Screening against AXL-expressing and non-expressing cancer cells was used to bias compound selection and evolution towards AXL inhibition." (PMID 33479617, 2020). "To elucidate the mechanism involved in AXL-mediated VM, we investigated the possible involvement of VEGF and FGF signaling previously reported to be important in VM, invasiveness, and angiogenesis of various cancers." (PMID 33374832, 2020). "As novelty in support of our previous data that hMENA/hMENAΔv6 participate at invadopodia maturation and mediate cancer cell invasiveness, herein we demonstrate that hMENA regulates the expression of the RTK AXL recently reported to be involved in the regulation of invadopodia formation." (PMID 32909687, 2020). "Inhibitors of AXL and MEK are promising anti-cancer therapeutics." (PMID 33283192, 2020). "However, given the cancer-intrinsic targets of Cabozantinib, both MET and AXL have been shown to participate in cell adhesion." (PMID 33041663, 2020). "Axl-148b conjugate was able to inhibit migration and invasion of AXL-positive, but not AXL-negative, cancer cells, demonstrating high efficacy and selectivity in vitro." (PMID 32174798, 2020). "It has been reported that BGB324 induced cancer cell apoptosis, but the role of AXL inhibition in BGB324-induced apoptosis has not been clarified." (PMID 31497246, 2019).
cancer (continued). "Deregulated oncogenic activity of the AXL receptor tyrosine kinase (AXL) and elevated levels of its ligand GAS6 (growth arrest specific gene 6) are found in numerous types of human cancer and are directly correlated with diverse aspects of cancer pathogenesis." (PMID 31171001, 2019). "This is different from AXL, which transduces a strong signal in cancer cells even in the absence of PtdSer." (PMID 31775787, 2019). "This review will focus on PtdSer as a cofactor required for stimulating TYRO3, AXL and MERTK – comprising the TAM family of receptor tyrosine kinases by their ligands Protein S (PROS1) and growth-arrest-specific 6 (GAS6) in inflammation and cancer." (PMID 31775787, 2019). "Combined inhibition of FLT3 and CDK6 reduced the severeness of cancer-promoting processes, but could still be bypassed by PI3K-mediated signalling involving the nodes PI3K, SHC and AXL resulting in potential treatment escape routes." (PMID 29699481, 2018). "The delineation of the exact mechanistic details downstream of BRAF/AXL and upstream of transcription factors that control RIPK3 transcription is likely to be of importance to our understanding of cancer escape from necroptosis and will be elucidated in future studies." (PMID 30157175, 2018). "This suggests AXL and HSP90 inhibitors may be promising therapeutic drugs to overcome drug-tolerant cancer cell subpopulations in ALK-positive NSCLC patients for the reason that ALK-positive NSCLC cells do not live through ALK-TKI therapy." (PMID 29930762, 2018). "Altogether, our data suggest the existence of a homeostatic balance between the intracellular trafficking and sequential processing of AXL-FL and the cellular localization of cleavage products sAXL/AXL-ICD in cancer cells, a balance that is maintained by α- and γ- secretases and the proteasome." (PMID 28034848, 2017). "Notably, MMP14 is ‐ together with AXL, caveolin 1 (CAV1) and ITGA5 ‐ among the top genes contributing to the differentiation of cancer from normal tissue." (PMID 28596300, 2017). "There are a number of ongoing cancer clinical trials aiming at inhibiting the activity of AXL kinase, such as using the novel small-molecule inhibitor R428 (BGB324) to potently block autophosphorylation of AXL." (PMID 28551766, 2017). "However, the prognostic role of co-expression of AXL and HER2 in cancer cells has hardly been investigated." (PMID 27172793, 2016). "Additionally, three suggestive pan-cancer DMPs (P < 1.0 × 10−5) were identified for probes cg26079695 in COL11A2, cg27094856 in AXL, and cg21046959 in LINC00340." (PMID 26798410, 2016). "In this respect, we found 1553 and 1061 genes defined as up-regulated or down-regulated, respectively, in AXL positive cancer cell lines (t test, p < 0.05) (data not shown)." (PMID 25966280, 2015). "Moreover, AXL has been demonstrated to exhibit high expression levels across various cancers but is absent in normal tissues, rendering it a potential target for cell-based therapy." (PMID 40299452, 2025). "Although AXL has been implicated in conferring drug resistance and mediating immunomodulatory functions, the therapeutic potential of AXL inhibition in potentiating ICI-based therapy in drug-resistant cancers, for example, HCC, has not been studied." (PMID 38310091, 2024). "AXL-signaling has also been shown to prevent cytotoxic T-cells from binding and killing NSCLC cells and is an important negative-feedback regulator of type I interferon-driven antitumor immunity, enabling cancers to resist ICI-mediated T-cell cytotoxicity in the long-term." (PMID 39238637, 2024). "The enzymatic processing of AXL leads to the production of sAXL, and plasma sAXL is significantly increased in HCC and PDAC, making it a candidate biomarker for early diagnosis of these cancers, thus highlighting the potential value of sAXL in cancer diagnosis and prognosis prediction." (PMID 37328828, 2023).
cancer (continued). "In addition, the M genes that exhibited dynamic compartment changes across the cancer cell lines were enriched in the biological process related to anatomical structure morphogenesis, including COL5A2, LOX, CDH2, ZEB1, and AXL (FDRdynamic = 1.22 × 10−8)." (PMID 35637517, 2022). "Among these proteins, AXL receptor tyrosine kinase (AXL), carbonic anhydrase IX (CA9), enolase 2 (ENO2), human epidermal growth factor receptor (HER) 1, HER2, HER3, progranulin (PRGN), and platelet-derived growth factor-AA (PDGF-AA) are primarily involved in cancer cell proliferation." (PMID 35745691, 2022). "Due to absent expression of AXL in cluster 5, it might not be an effective strategy for those cancer cell lines." (PMID 34006939, 2021). "However, our findings suggest that AXL and the PI3K/AKT pathways may provide additional combination strategies in conjunction with BETi to improve response rates in lung and other cancers." (PMID 33712563, 2021). "Furthermore, no study has been reported on the LAMP of AXL genes as a potential candidate for the diagnosis of certain cancers." (PMID 34442532, 2021). "To investigate the role of hMENA in ligand‐dependent AXL signaling, we treated PANC‐1 cells with rGAS6 and we found that hMENA silencing inhibits GAS6‐mediated AXL and AKT phosphorylation and reduced cancer cell invasion toward GAS6 as detected by Matrigel transwell invasion assay." (PMID 32909687, 2020). "It has been reported that BGB324 induced apoptosis in cancer cells may be dependent or independent of AXL inhibition." (PMID 33396393, 2020). "Therefore, it is important to further clarify the biological roles of AXL in the context of anti-PD-1 or PD-L1 therapy, to develop novel approaches in cancer therapy." (PMID 31497246, 2019). "Given that PTBP1 may destabilize AXL mRNA, it would be interesting to investigate, in cells expressing no or little PTBP1, whether AXL inhibitors may effectively inhibit cancer cells growth because of the potential likelihood of their AXL-dependency." (PMID 31729427, 2019). "A 4-day treatment of A375 and SkMel28 cancer cell lines, which have no initial RIPK3 expression (but also no genetic mutations of RIPK3), with low concentrations of AXL/TYRO3 inhibitor BMS-777607 resulted in a regain of RIPK3 expression at both mRNA and protein levels." (PMID 30157175, 2018). "It is tempting to speculate that the observed increase, rather than the expected decrease, in soluble plasma AXL levels is a manifestation of its increased expression in cancer cells that is in turn a result of cabozantinib-induced-hypoxia." (PMID 26762579, 2016). "Furthermore, they found that 44 could inhibit the migration and invasion of Panc-1 cells by downregulating FAK (a downstream mediator of AXL) activity and reducing the expression of the matrix metalloproteinases MMP-2 and MMP-9, which are responsible for initiating metastasis of cancer cells." (PMID 39275088, 2024). "Additionally, AXL can be cleaved by the A disintegrin and metalloproteinases (ADAM) 10 and ADAM17 to generate soluble AXL (sAXL), which inhibit AXL function and could be a promising biomarker for predicting cancer progression." (PMID 37328828, 2023). "Interestingly, the proteasome‐dependent degradation of full‐length AXL (AXL‐FL) has been reported to couple with production of AXL intracellular domain (ICD), and AXL‐ICD could regulate the expression of cancer‐related genes, which is believed to be one of the ligand‐independent functions of AXL." (PMID 36409270, 2023). "Therefore, AXL and TGFβ receptors expression was assessed on mRNA and protein level in a panel of human CRC cell lines (HCT116, SW480, LoVo, SW48, LIM1215) including three RAS-mutant (RASm) (HCT116, SW480, and LoVo) and two RAS wild-type (RASwt) (SW48, LIM1215) cancer cell lines." (PMID 33570712, 2021).
cancer (continued). "Meanwhile, it will be interesting to see whether known transcription factors that regulate AXL synthesis (i.e., activator protein AP1, YAP/TAZ/TEAD, and HIF1α) can mediate the predominant activation AXL and promote EGFR-TKI-specific resistance trajectory in chemoresistant cancer cells." (PMID 33850249, 2021). "However, whether AXL overexpression in TECs promotes vessel metastasis in patients with HCC through modulating cancer metabolism has not yet been clarified." (PMID 34123800, 2021). "Our data suggested that inhibition of MET and AXL phosphorylation activities through LY2801653 in turn led to marked suppression of downstream oncogenic signaling pathways, which might play important roles in proliferation and angiogenesis‐related behaviors of cancer." (PMID 34766112, 2020). "Furthermore, our results show that simultaneous inhibition of AXL and MET exerted superior inhibitory effects on cancer cell migration compared to individual inhibition, suggesting that combinatorial inhibition of various oncogenic signals effectively suppresses cancer progression." (PMID 32055714, 2020). "Thus YAP expression and activation may be a reason for AXL induction in drug-resistant adenocarcinomas and some other cancer types; though we did not evaluate AXL expression following YAP knockdown, which would have been interesting." (PMID 28680534, 2017). "Nevertheless, cell sorting according to resistant markers, such as AXL or NFGR, enriched the pre-resistant cells in some but not all cell lines, suggesting that the resistance mechanism is cell line-dependent and cancer-dependent." (PMID 35740696, 2022). "Among the assessed mRNAs that were present in cancer-derived EVs and absent in MCF10A-derived EVs, several genes, including SNAIL1/2, TAZ, AXL, RHOA and ROCK1, are well known to promote cell motility." (PMID 33921957, 2021). "We profiled the expression of MER among multiple human cancer cells and found that MER and TYRO3, but not AXL, show high levels of protein expression in G361 cells." (PMID 32042425, 2020). "The LuCSC-holoclones were EpCAM+ (morphologically epithelial), and negative for classical EMT genes AXL, CD10, Zeb1 and MMP1 that are involved in motility and invasive behavior of mesenchymal cancer cells." (PMID 31069016, 2019). "In the present study, we systematically characterized the proteolytic process of TAM receptors and found that AXL, but not MERTK or TYRO3, is efficiently and sequentially processed by α- and γ-secretases in 7 types of cancer cells." (PMID 28034848, 2017). "We found that AXL-FL, but not MERTK or TYRO3, was very efficiently cleaved by α- and γ-secretases in various types of cancer cell lines." (PMID 28034848, 2017). "In the present study, we demonstrate that AXL, but not TYRO3 or MERTK, is efficiently and sequentially cleaved by α- and γ-secretases in various types of cancer cell lines." (PMID 28034848, 2017). "The VEGFR1 kinase expression was higher than AXL in MPM, however, the VEGF ligand (VEGFA gene) was not expressed in MPM as high as most other cancers in the dataset (ranking #20 of 30)." (PMID 29375377, 2017). "Moreover, TAM (TYRO3, AXL, and MERTK) family also had negative influence on cancer immunotherapy by mediating efferocytosis, negative regulating of dendritic cell activity, and dysregulating production of chemokines." (PMID 36341335, 2022). "In addition, it has been demonstrated that hepatocyte growth factor (HGF) induces AXL phosphorylation, independent of GAS6, and that the Met-AXL-Elmo2-Dock180 complex is critical for HGF-induced migration of cancer cells." (PMID 31694201, 2019). "Consequently, a small molecule inhibitor specific to AXL (R428; also known as BGB-324 or Bemcentinib) is currently under investigation in a phase II clinical trial for various cancers, including non-operable and metastatic TNBC." (PMID 31007848, 2019).